PLAC8 (placenta associated 8)
Synonyms: onzin; C15; DGIC; PNAS-144
Tractability: Antibody: its Gene Ontology location is reachable by antibodies, with high confidence.
Gene: Protein-coding gene on chromosome 4 (83,059,493 to 83,137,075, reverse strand). Ensembl gene ENSG00000145287.
Subcellular location (Human Protein Atlas): Cytosol
Pathways (Reactome):
Developmental Biology: Formation of the nephric duct
Immune System: Neutrophil degranulation
Gene Ontology:
Molecular function: chromatin binding
Biological process: positive regulation of cold-induced thermogenesis; positive regulation of transcription by RNA polymerase II
Cellular component: azurophil granule lumen; extracellular region
Genetic constraint (gnomAD): Loss-of-function variants: 3 observed, 7.41 expected, observed/expected ratio (o/e) 0.4, 90% interval 0.18 to 1.05. That is too few expected variants to judge how well the gene tolerates losing a copy. Missense variants: 79 observed, 96.48 expected, observed/expected ratio (o/e) 0.82, 90% interval 0.68 to 0.99. Synonymous variants: 39 observed, 38.21 expected, observed/expected ratio (o/e) 1.02, 90% interval 0.79 to 1.33.
Homologues: Orthologues: chimpanzee PLAC8 (100% identical), macaque PLAC8 (93% identical), dog PLAC8 (88% identical), guinea pig PLAC8 (86% identical), rabbit PLAC8 (83% identical), rat Plac8 (83% identical), mouse Plac8 (82% identical), zebrafish plac8.1 (44% identical), zebrafish plac8.2 (43% identical). Paralogues in human: CNFN (36% identical), PLAC8L1 (36% identical).
Diseases named in the same sentence as PLAC8 in open-access papers:
PLAC8 is named in the same sentence as 74 diseases in open-access papers, as found by Europe PMC text mining. Sharing a sentence is not in itself a finding about the gene and the disease. The quoted sentences say what the papers report.
Sepsis (13 papers, 2015 to 2025). Sepsis is defined as life-threatening organ dysfunction caused by a dysregulated host response to infection. "Other placenta-related genes e.g., PLAC8 have also been reported in association with immune processes including sepsis, however wider tissue expression of this latter gene has already been mapped and its association with immune cells and function confirmed." (PMID 32318053, 2020). "In sepsis mice, Plac8 overexpression similarly activated the ERK pathway and promoted the survival, proliferation, and activation of monocytes." (PMID 38961068, 2024). "Higher expression levels of CD63 and PLAC8 in sepsis than SIRS reached statistical significance in both total and LD granulocytes." (PMID 39434093, 2024). "This study aimed to investigate the effect of Plac8 upregulation on monocyte proliferation and activation in sepsis patients." (PMID 38961068, 2024). "Activation of the ERK pathway significantly influences the proliferation and activation of monocytes by Plac8, providing a novel perspective for understanding the pathophysiology of sepsis." (PMID 38961068, 2024). "This indicates that, as expected, the increased sepsis levels of CD63 compared to SIRS largely stem from immature granulocytes but that PLAC8 expression is additionally increased in PMNs." (PMID 39434093, 2024). "In the inflammatory disease model of sepsis, Plac8 is involved in the activation and apoptosis of inflammatory cells." (PMID 38961068, 2024). "The results showed that Plac8 was highly expressed in sepsis models, promoting the survival, proliferation, and activation of monocytes." (PMID 38961068, 2024). "SeptiCyte® RAPID is a gene expression assay measuring the relative expression levels of host response genes PLA2G7 and PLAC8, indicative of a dysregulated immune response during sepsis." (PMID 36851633, 2023). "Among the azurophilic granule genes, PLAC8 showed, on average, the strongest fold increase in both sepsis and SIRS compared to presurgical patients." (PMID 35844509, 2022). "Recently, many genes have also been identified for sepsis diagnosis and prognosis; for example, SeptiCyte Lab combined with CEACAM4, LAMP1, PLA2G7, and PLAC8 genes was identified to determine which patients had sepsis." (PMID 32922168, 2020). "SeptiCyte® RAPID (Seattle, WA, USA) also represents a novel diagnostic tool that assesses the host immune response by quantifying PLA2G7 and PLAC8 gene expression in whole blood, offering potential for early differentiation between sepsis and sterile inflammation." (PMID 41096721, 2025). "Building upon the theoretical foundation of this study, clinical applications could explore interventions targeting Plac8 specific to PBMCs to provide effective solutions for precise sepsis treatment." (PMID 38961068, 2024). "However, further exploration is needed to understand how Plac8 maintains this balance in sepsis, which could have important implications for developing new treatment strategies." (PMID 38961068, 2024). "It suggests that Plac8 may play a role in sepsis through the signaling pathway mediated by ERK." (PMID 38961068, 2024). "In the LD granulocytes by contrast, the sepsis-SIRS differences in CD63 and PLAC8 expression were comparable." (PMID 39434093, 2024). "The test provided a probability of sepsis, based on measurement of four host immune response biomarkers—PLA2G7, PLAC8, CEACAM4 and LAMP1." (PMID 38592057, 2024). "The granule biogenesis pathway genes CEACAM4, PLAC8, and CD63 were analyzed by quantitative real-time polymerase chain reaction (qRT-PCR) and their abilities to distinguish sepsis and SIRS were compared to the routine infection marker CRP (C-reactive protein)." (PMID 39434093, 2024). "By qRT-PCR, the azurophilic granule genes CD63 and PLAC8 showed higher sepsis than SIRS levels in LD granulocytes and PLAC8 also in total granulocytes where its discriminatory performance resembled C-reactive protein (CRP)." (PMID 39434093, 2024).
Sepsis (continued). "In conclusion, the upregulation of Plac8 enhances the activation of the ERK pathway and promotes monocyte proliferation and activation in sepsis patients." (PMID 38961068, 2024). "But using the levels of CEACAM4 in the HD fraction as a reference for PLAC8, also a SeptiCyteTM LAB gene, and CD63 in the LD fraction still improved the sepsis-SIRS distinction by these two azurophilic granule genes compared to their unreferenced LD levels." (PMID 39434093, 2024). "In the current study, PLAC8 expression in total granulocytes rivaled the discriminatory performance of CRP, showing a twofold larger increase in sepsis than CRP." (PMID 39434093, 2024). "Thus, further research on the interaction between the ERK pathway and Plac8 is crucial for unraveling the complex network of immune cell function in sepsis pathology, providing new insights that could potentially form the basis for future targeted intervention strategies." (PMID 38961068, 2024). "For instance, the first host response gene expression assay for diagnosis of sepsis, SeptiCyte LAB, is based on the four marker genes CEACAM4, LAMP1, PLAC8 and PLA2G7." (PMID 34555028, 2021). "Interestingly, unreferenced PLAC8 showed the largest and CD63 the smallest sepsis-SIRS difference in total granulocytes, whereas for both genes the sepsis-SIRS differences in the LD fractions were comparable." (PMID 39434093, 2024). "Furthermore, the Plac8/ERK signaling pathway has been confirmed to be involved in regulating cell proliferation, yet its role in sepsis remains insufficiently explored." (PMID 38961068, 2024). "Taken together, this indicates that elevated expression of CD63 but not PLAC8 in sepsis is restricted to LD granulocytes and that a concomitant reduction of CEACAM4 expression in HD granulocytes improves the ratiometric discrimination between sepsis and SIRS." (PMID 39434093, 2024).
breast carcinoma (12 papers, 2010 to 2025). "Placenta associated 8 (PLAC8), a recently identified substrate of UFMylation, has been implicated in breast cancer pathogenesis." (PMID 39259506, 2024). "In this study, we further determined whether the feedback increase of PLAC8 might be associated with the response to tamoxifen in breast cancer." (PMID 33611659, 2021). "Thus, our findings suggested that ADM induced up‐regulation of PLAC8, and the intrinsically and acquired resistance to ADM in breast cancer may partially be caused by PLAC8 overexpression." (PMID 34117724, 2021). "Our results clarified the underlying relationship between the PLAC8 and curcumin in BC.To the best of our knowledge, we are the first to demonstrate that curcumin increases the ubiquitin of PLAC8 protein and augments endocrine-sensitivity to tamoxifen in breast cancer in vitro and in vivo." (PMID 33611659, 2021). "PLAC8/MAPK (mitogen-activated protein kinase) axis regulated tamoxifen sensitivity in breast cancer, which was abrogated by curcumin-mediated protein stability change." (PMID 39247188, 2024). "For example, one study found PLAC8 induction to promote cell proliferation in breast cancer, while another reported inhibitory actions in hepatocellular carcinoma." (PMID 37759443, 2023). "The localization of PLAC8 in breast cancer cells (MDA‐MB231, MCF‐7 and MCF‐7/ADMR) was detected using immunofluorescence staining, and PLAC8 was localized in both the nucleus and cytosol of breast cancer cells." (PMID 34117724, 2021). "Our findings proposed that PLAC8 contributed to ADM resistance in breast cancer via modulation of autophagy." (PMID 34117724, 2021). "We demonstrated that the knockdown of PLAC8 by the ubiquitin increased the sensitivity of tamoxifen in breast cancer cells." (PMID 33611659, 2021). "Immunohistochemistry analysis of PLAC8 protein further confirmed the previous results that ADM‐resistant breast cancer tended to be PLAC8‐overexpressed." (PMID 34117724, 2021). "We previously shown that PLAC8 collaborates with p62 to suppress autophagy in doxorubicin resistant breast cancer cells." (PMID 34627411, 2021). "And reversely, PLAC8 overexpression by transfection with a pcDNA3.1(C)‐PLAC8 plasmid conferred protection from ADM for breast cancer cell." (PMID 34117724, 2021). "The results revealed that PLAC8 overexpression in MCF‐7 conferred protection from ADM for breast cancer cell MCF‐7." (PMID 34117724, 2021). "Here, we found higher PLAC8 expression was correlated with worse outcome and aggressive phenotype in breast cancer." (PMID 34117724, 2021). "On the other hand, PLAC8 upregulates N-cadherin and vimentin levels in breast cancer and nasopharyngeal carcinoma cells." (PMID 34627411, 2021). "Our study highlighted that breast cancer cells with high PLAC8 expression responded weakly to ADM treatment, and PLAC8 was necessary and sufficient in inducing ADM‐resistant phenotype." (PMID 34117724, 2021). "In contrast, combined therapy of siRNA‐mediated PLAC8 depletion with RAPA treatment sensitized breast cancer cells to ADM treatment." (PMID 34117724, 2021). "From our two previously published studies, PLAC8 was relatively highly expressed in lung cancer and breast cancer tissues, and contributed to cancer progression." (PMID 34117724, 2021). "In our studies, high PLAC8 expression is correlated with breast cancer resistant to ADM and poor outcome." (PMID 34117724, 2021). "A recent study demonstrated that PLAC8 contributes to cell proliferation and suppresses cell apoptosis in breast cancer by activating the PI3K/AKT/NF-κB pathway." (PMID 35223452, 2021). "In breast cancer cells, embryonic kidney 293 T cells, colorectal cancer cells and nasopharyngeal carcinoma cells, PLAC8 downregulates the level of E-cadherin thus regulating cell migration and invasion." (PMID 34627411, 2021). "In this study, we examined the clinical significance and biological effects of PLAC8 in breast cancer progression and ADM sensitivity regulation." (PMID 34117724, 2021).
breast carcinoma (continued). "Our study found that overexpression of PLAC8 can promote tamoxifen resistance in breast cancer and that the expression of PLAC8 can be reduced by curcumin." (PMID 34627411, 2021). "An in‐depth understanding of the mechanisms of PLAC8/autophagy regulation in relation to ADM resistance will provide a promising therapeutic strategy for overcoming ADM resistance of breast cancer treatment." (PMID 34117724, 2021). "The results from the breast cancer dataset (GSE24460) also showed that PLAC8 expression was significantly up‐regulated in the resistant MCF‐7 cells compared with the parental MCF‐7 cells." (PMID 34117724, 2021). "We have confirmed that PLAC8 can suppress breast cancer apoptosis by activating the PI3k/AKT/NF-κB pathway." (PMID 33611659, 2021). "Increased expression of PLAC8 has been reported in putative cancer stem cells in liver and breast cancer cell lines." (PMID 20618946, 2010). "Collectively, curcumin could inhibit breast cancer cell proliferation, migration, invasion, and reverse tamoxifen resistance through affecting PLAC8 protein stability." (PMID 33611659, 2021). "PLAC8 plays critical role in the development and progression of breast cancer." (PMID 34117724, 2021). "Here we found that PLAC8 could be a new prognostic marker in breast cancer, and there is a potential relationship between PLAC8 expression and ADM resistance." (PMID 34117724, 2021). "In addition, the expression of PLAC8 can be reduced by curcumin in tamoxifen resistant breast cancer." (PMID 34627411, 2021). "In addition, PLAC8 has been found in nasopharyngeal carcinoma and breast cancer cell cytoplasm and membrane." (PMID 34627411, 2021). "Breast cancer patients with higher PLAC8 expression showed potential ADM resistance." (PMID 34117724, 2021). "We then assessed PLAC8 regulation to autophagy in breast cancer cells." (PMID 34117724, 2021). "Our previous study proved that PLAC8 was involved in the breast cancer progression." (PMID 33611659, 2021). "Compared to that in breast normal tissues, PLAC8 expression was elevated in breast cancer." (PMID 34117724, 2021). "We found that PLAC8 inhibits breast cancer cell apoptosis, thus promoting cell proliferation." (PMID 34627411, 2021). "And combined treatment of autophagy inducer RAPA and PLAC8 knockdown could efficiently reverse ADM resistance in breast cancer." (PMID 34117724, 2021). "Our experiments suggested that PLAC8 may affect ADM sensitivity by modulating autophagy in breast cancer." (PMID 34117724, 2021). "Moreover, autophagy inhibitors 3‐MA promoted accumulation of autophagic vacuoles and enhanced the cytoprotective effect induced by PLAC8 overexpression to ADM cytotoxicity in the breast cancer cell." (PMID 34117724, 2021). "PLAC8/p62 pathway may act as novel therapeutic targets in breast cancer treatment and has potential clinical application in overcoming ADM resistance." (PMID 34117724, 2021). "Additionally, the down‐regulation of p62 by siRNA attenuated the activation of autophagy and PLAC8 expression in breast cancer cells." (PMID 34117724, 2021). "PLAC8 could also promote proliferation and inhibit apoptosis in breast cancer cells by activating the PI3K/AKT/NF- κB pathway." (PMID 32903581, 2020). "PLAC8 may alter the ADM sensitivity of breast cancer cells by modulating autophagy process." (PMID 34117724, 2021). "We overexpressed PLAC8 in MCF‐7 cell and construct the stable PLAC8 overexpression breast cancer cell (C1 and C2 clones) (respectively) and then analysed the cell response to ADM." (PMID 34117724, 2021). "In this study, we firstly reported the potential correlation between elevated PLAC8 expression level and ADM resistance in breast cancer tissues." (PMID 34117724, 2021). "We next tested these breast cancer cells response to ADM, and explore the potential correlation between PLAC8 expression and ADM resistance." (PMID 34117724, 2021).
breast carcinoma (continued). "Here, our findings suggested that PLAC8 inhibited autophagy at least partially through the participation of p62 and then affected ADM resistance in breast cancer cells." (PMID 34117724, 2021). "However, whether PLAC8 is involved in tamoxifen resistance in breast cancer is still unclear." (PMID 33611659, 2021). "To examine roles of PLAC8 in ADM sensitivity in breast cancer, we next tested the PLAC8 expression profile in a range of breast cancer cell lines." (PMID 34117724, 2021). "However, the precise function of PLAC8 in breast cancer (BC) progression remains unclear." (PMID 31448883, 2019). "Clinical data from breast cancer patients further revealed that PLAC8 expression was elevated in TNBC compared to non-TNBC and was associated positively with PD-L1 expression." (PMID 39247188, 2024). "Depending on the clinical tumour subtype, the triple‐negative and HER2‐positive breast cancer presented relatively higher PLAC8 expression, compared to the luminal‐type, normal‐like and unclassified type of breast cancer (P < .00001)." (PMID 34117724, 2021). "Thus, our findings suggest that PLAC8, through the participation of p62, inhibits autophagy and consequently results in ADM resistance in breast cancer." (PMID 34117724, 2021). "In addition to endocrine resistance, PLAC8 regulates RAC1 levels, and another study has reported that RAC1 promotes breast cancer chemoresistance by influencing DNA damage repair." (PMID 34627411, 2021). "Furthermore, enforced overexpression or inhibition of PLAC8 could modulate autophagy through p62 participation and thus altered ADM sensitivity in breast cancer cells." (PMID 34117724, 2021). "The inhibition of PLAC8 expression and MAPK pathway by curcumin enhanced breast cancer cell sensitivity to tamoxifen and suggested that curcumin could be served as a effective drug for tamoxifen resistant breast cancer." (PMID 33611659, 2021). "Besides, the IC50 of ADM was much lower in T47D and MCF‐7 cells than MDA‐MB231 and MCF‐7/ADMR cells, suggesting that increased PLAC8 expression might play an essential role in both intrinsically and acquired ADM resistance in breast cancer cells." (PMID 34117724, 2021). "PLAC8 may be used as a novel biomarker in the prediction of patient responsiveness to ADM and serves as a unique therapeutic target for overcoming ADM resistance in breast cancer." (PMID 34117724, 2021). "The role of PLAC8 in the regulation of autophagy and ADM resistance in breast cancer has not been reported until now." (PMID 34117724, 2021).
colon carcinoma (7 papers, 2010 to 2023). "MxIF has analyzed the expression of 61 protein antigens in 747 colon cancer samples and even identified that placenta-specific 8 (PLAC8) as a molecule contributed to colon cancer invasion." (PMID 36834500, 2023). "The oncogenic role of PLAC8 was reported in the early stages of pancreatic cancer, prostate cancer, and colon cancer cells, exhibiting increased PLAC8 levels, which showed epithelial–mesenchymal transition features and resulted in tumor invasion." (PMID 29789534, 2018). "In colon cancer, PLAC8-overexpressing cells exhibited increased phosphorylated extracellular signal-regulated kinase 2, which led to elevated cell motility and cancer invasion." (PMID 29789534, 2018). "Interestingly, in colon cancer, PLAC8-overexpressing cells exhibited elevated cell motility and cancer invasion." (PMID 37582932, 2023). "Interestingly, PLAC8 is reported to be a candidate oncogene and is known to affect regulation of autophagy and promote ERK-dependent epithelial mesenchymal transition in colon cancers." (PMID 26808319, 2016).